MUSK (muscle associated receptor tyrosine kinase)
Description:
Receptor tyrosine kinase which plays a central role in the formation and the maintenance of the neuromuscular junction (NMJ), the synapse between the motor neuron and the skeletal muscle. Recruitment of AGRIN by LRP4 to the MUSK signaling complex induces phosphorylation and activation of MUSK, the kinase of the complex. The activation of MUSK in myotubes regulates the formation of NMJs through the regulation of different processes including the specific expression of genes in subsynaptic nuclei, the reorganization of the actin cytoskeleton and the clustering of the acetylcholine receptors (AChR) in the postsynaptic membrane. May regulate AChR phosphorylation and clustering through activation of ABL1 and Src family kinases which in turn regulate MUSK. DVL1 and PAK1 that form a ternary complex with MUSK are also important for MUSK-dependent regulation of AChR clustering. May positively regulate Rho family GTPases through FNTA. Mediates the phosphorylation of FNTA which promotes prenylation, recruitment to membranes and activation of RAC1 a regulator of the actin cytoskeleton and of gene expression. Other effectors of the MUSK signaling include DNAJA3 which functions downstream of MUSK. May also play a role in acetylcholinesterase (AChE) localization at the neuromuscular junctions (NMJ) via its interaction wit COLQ (By similarity). May also play a role within the central nervous system by mediating cholinergic responses, synaptic plasticity and memory formation (By similarity).
Synonyms: CMS9; FADS
Tractability: Small molecule: a high-quality ligand is known; it belongs to a druggable protein family. Antibody: UniProt places it where antibodies can reach, with high confidence; UniProt predicts a signal peptide or a membrane-spanning region; its Gene Ontology location is reachable by antibodies, with medium confidence. PROTAC: UniProt records ubiquitination sites on it; a small molecule that binds it is known.
Target class: Enzyme; Tyrosine protein kinase Musk family; Protein Kinase; TK protein kinase group; Kinase
Gene: Protein-coding gene on chromosome 9 (110,668,779 to 110,806,558, forward strand). Ensembl gene ENSG00000030304.
Subcellular location: Postsynaptic cell membrane
Pathways (Reactome):
Extracellular matrix organization: ECM proteoglycans
Gene Ontology:
Molecular function: protein binding; protein tyrosine kinase activity; transmembrane receptor protein tyrosine kinase activity; Wnt-protein binding; ATP binding; PDZ domain binding; protein kinase activity
Biological process: neuromuscular junction development; positive regulation of protein phosphorylation; cell surface receptor protein tyrosine kinase signaling pathway; memory; positive regulation of gene expression; positive regulation of protein geranylgeranylation; regulation of synaptic assembly at neuromuscular junction; skeletal muscle acetylcholine-gated channel clustering; enzyme-linked receptor protein signaling pathway; positive regulation of Rac protein signal transduction; positive regulation of skeletal muscle acetylcholine-gated channel clustering
Cellular component: postsynaptic membrane; receptor complex; neuromuscular junction; plasma membrane; membrane; synapse
Genetic constraint (gnomAD): Loss-of-function variants: 50 observed, 81.37 expected, observed/expected ratio (o/e) 0.61, 90% interval 0.49 to 0.78. The upper end of that interval is the gene's LOEUF score, 0.78, which puts it in group 3 of 6, group 1 being the genes least tolerant of losing a copy. Missense variants: 941 observed, 1,054.3 expected, observed/expected ratio (o/e) 0.89, 90% interval 0.85 to 0.94. Synonymous variants: 372 observed, 390.83 expected, observed/expected ratio (o/e) 0.95, 90% interval 0.87 to 1.04.
Homologues: Orthologues: chimpanzee MUSK (99% identical), macaque MUSK (99% identical), pig MUSK (95% identical), guinea pig MUSK (94% identical), rat Musk (93% identical), mouse Musk (92% identical), dog MUSK (91% identical), rabbit MUSK (87% identical), tropical clawed frog musk (73% identical), Drosophila melanogaster Nrk (30% identical). Paralogues in human: NTRK1 (25% identical), NTRK3 (25% identical), NTRK2 (24% identical), ROR1 (24% identical), ROR2 (23% identical), ROS1 (22% identical), IGF1R (20% identical), TYRO3 (20% identical), TIE1 (20% identical), MERTK (20% identical), TEK (20% identical), FGFR4 (19% identical), and 41 more.
Diseases named in the same sentence as MUSK in open-access papers:
MUSK is named in the same sentence as 107 diseases in open-access papers, as found by Europe PMC text mining. Sharing a sentence is not in itself a finding about the gene and the disease. The quoted sentences say what the papers report.
myasthenia gravis (211 papers, 2011 to 2026). Myasthenia gravis (MG) is a rare, clinically heterogeneous, autoimmune disorder of the neuromuscular junction characterized by fatigable weakness of voluntary muscles. "Autoantibodies targeting MuSK cause myasthenia gravis (MG), a disease characterized by skeletal muscle weakness." (PMID 39898046, 2025). "Like MG, muscle-specific tyrosine kinase myasthenia gravis (MuSK MG) is an autoimmune disease that causes life-threatening muscle weakness due to anti-MuSK autoantibodies that disrupt neuromuscular junction signaling." (PMID 40103816, 2025). "A muscle-specific tyrosine kinase (MuSK) CAAR T was subsequently devised for MuSK myasthenia gravis (MG), a neuromuscular autoimmune disease caused by anti-MuSK autoantibodies." (PMID 39821376, 2025). "The role of MuSK in maintaining muscle size has potential implications for myasthenia gravis (MG) caused by autoantibodies to MuSK (“MuSK-MG”)." (PMID 38172960, 2024). "A clinical trial (NCT05451212) is underway to test MuSK-CAAR T cells in patients with anti-MuSK antibody-associated myasthenia gravis." (PMID 39628482, 2024). "Muscle-specific kinase (MuSK)- myasthenia gravis (MG) is caused by pathogenic autoantibodies against MuSK that correlate with disease severity and are predominantly of the IgG4 subclass." (PMID 38715598, 2024). "Muscle-specific tyrosine kinase myasthenia gravis (MuSK MG) is a chronic autoimmune disorder caused by MuSK autoantibodies that result in potentially life-threatening muscle weakness." (PMID 36658341, 2023). "Muscle-specific tyrosine kinase myasthenia gravis (MuSK MG) is an autoimmune disease that causes life-threatening muscle weakness due to anti-MuSK autoantibodies that disrupt neuromuscular junction signaling." (PMID 36658341, 2023). "Couple of studies have also reported the association between MuSK antibody‐associated myasthenia gravis and SARS‐CoV‐2." (PMID 36306401, 2022). "Myasthenia gravis (MG) is an autoimmune disorder mediated by autoantibodies, including anti-acetylcholine receptor (AChR) or anti-muscle associated receptor tyrosine kinase (MUSK) antibodies that target the neuromuscular junction." (PMID 35463153, 2022). "The underlying mechanism of MuSK‐associated Myasthenia Gravis is more likely the breakdown in self‐tolerance mechanisms than cross‐reactivation given their molecular differences." (PMID 36306401, 2022). "Several cases of MuSK Antibody-Associated Myasthenia Gravis with SARS-CoV-2 infection have been reported." (PMID 35625805, 2022). "In patients, evidence accumulated for the pathophysiological importance of the MuSK CRD domain either by being linked to mutations in congenital myasthenic syndromes or by detection of autoantibodies in myasthenia gravis." (PMID 36552732, 2022). "Myasthenia gravis is an autoimmune disease mediated by B cells and is associated with acetylcholine receptor (AChR) and muscle-specific receptor tyrosine kinase (MuSK) antibodies in the postsynaptic membrane at the neuromuscular junction." (PMID 35633954, 2022). "A specific example relates to myasthenia gravis (MG) associated with predominantly IgG4 autoantibodies against muscle-specific kinase (MuSK), where autoreactive ASCs appear to be short-lived." (PMID 34220839, 2021). "The use of rituximab (RTX), an anti-CD20 monoclonal antibody (Ab), in refractory myasthenia gravis (MG) is associated with a better response in patients with Abs to the muscle-specific tyrosine kinase (MuSK) than in other MG subgroups." (PMID 32431692, 2020). "Myasthenia gravis (MG) is an autoimmune disease mediated by antibodies against the acetylcholine receptor (anti-AchR), the muscle-specific kinase (anti-MuSK) or other proteins associated with the postsynaptic membrane of the neuromuscular junction." (PMID 33148186, 2020). "In myasthenia gravis, the presence of anti-MuSK antibodies is associated with marked bulbar symptoms, which tend to cause problems in swallowing and difficulty in handling secretions." (PMID 26783473, 2015).
myasthenia gravis (continued). "Muscle-specific kinase (MuSK) belongs to the nicotinic acetylcholine receptor complex which is targeted by pathogenic autoantibodies causing Myasthenia gravis." (PMID 24416182, 2014). "In humans, 5–10% cases of myasthenia gravis are caused by autoantibodies against MuSK, which prevent binding between MuSK and Lrp4, and inhibit agrin-stimulated MuSK phosphorylation." (PMID 25540609, 2014). "For example, mutations in the AChR-associated protein of the synapse (rapsyn) and the muscle specific kinase (MuSK) lead to (recessive) myasthenic syndromes; antibodies against MuSK cause myasthenia gravis." (PMID 24065983, 2013). "These subgroups include AChR antibody‐positive generalized, ocular or thymoma‐associated myasthenia gravis, MuSK (muscle‐specific tyrosine kinase) and LRP4 (low density lipoprotein receptor‐related protein 4) antibody‐positive myasthenia gravis, and seronegative myasthenia gravis." (PMID 40298067, 2025). "Myasthenia gravis (MG) is an autoimmune disease caused mainly by pathological autoantibodies against components expressed at neuromuscular junctions, such as acetylcholine receptor (AChR) and muscle-specific tyrosine kinase (MuSK)." (PMID 38751878, 2024). "Antibodies targeting MUSK, which we found to be elevated in DS and associated with co-occurring neurological phenotypes, have been linked to development of myasthenia gravis, a chronic autoimmune neuromuscular disease that causes weakness in the skeletal muscles." (PMID 39737640, 2024). "Myasthenia gravis (MG) is characterized by fluctuating muscle weakness caused by autoantibodies against the acetylcholine receptor (AChR) and the muscle-specific tyrosine kinase (MuSK)." (PMID 35624411, 2022). "In contrast, genes coding for the acetylcholine receptor (CHRNA1), the muscle antigen titin (TTN), and MUSK, which are associated with the neuromuscular autoimmune disease myasthenia gravis, were predominantly found in the myoid, neuroendocrine, and ciliated subsets." (PMID 33597545, 2021). "Observations indicate that patients with different subtypes of myasthenia gravis, associated with the presence of different antibodies—AChR, MuSK, or against lipoprotein receptor-related protein 4 (LRP4)—present similar clinical symptoms, regardless of the mechanism of immunopathology." (PMID 34439676, 2021). "These Ab may originate from peripheral antibody-secreting cells after post-germinal centre affinity maturation which then transit into the CNS as seen in AQP4 Ab-associated NMOSD and MuSK Ab-associated myasthenia gravis." (PMID 31481127, 2019). "Finally, autoantibodies to the acetylcholine receptor (AChR) and to muscle-specific kinase (MuSK) are associated with myasthenia gravis (MG)." (PMID 30824481, 2019). "These include acetylcholine receptor (AChR), muscle-specific kinase (MuSK), lipoprotein receptor-related protein 4 (Lrp4), all associated with myasthenia gravis (MG), and voltage-gated calcium channel (VGCC) associated with PNS Lambert-Eaton myasthenic syndrome (LEMS)." (PMID 27577085, 2016). "For example, in myasthenia gravis associated with MuSK antibodies, both IgG1 and IgG4 antibodies affect acetylcholine receptor cluster stability in cultures of myotubes through different mechanisms, but only IgG4 antibodies can reproduce the disease in experimental animal models." (PMID 27586161, 2016). "Impairments of MuSK phosphorylation have been associated with several disorders, such as myasthenia gravis (MG) and congenital myasthenia (CMS)." (PMID 36105254, 2022). "Myasthenia gravis (MG) is an acquired autoimmune disorder caused by autoantibodies binding acetylcholine receptors (AChR), muscle‐specific kinase (MuSK), agrin or low‐density lipoprotein receptor‐related protein 4 (Lrp4)." (PMID 34228850, 2021).
myasthenia gravis (continued). "Myasthenia gravis (MG) is a rare disease of the neuromuscular junction caused by Abs against postsynaptic membrane proteins, such as the acetylcholine receptor (AChR), the muscle-specific tyrosine kinase (MuSK), or the low-density receptor-related protein 4 (LRP4)." (PMID 32431692, 2020). "The most accepted classification divides myasthenia gravis into the following subgroups: ocular; thymoma-associated; early onset and late-onset generalized with antibodies against acetylcholine receptor (AChR), anti-muscle specific tyrosine kinase (MuSK) positive and double seronegative." (PMID 33324944, 2020). "In 2001, serum antibodies against muscle-specific tyrosine kinase (MuSK-Abs) were identified for the first time as cause of myasthenia gravis (MG), opening the way to the description of a distinct peculiar subtype of MG disease." (PMID 32793097, 2020). "Myasthenia gravis (MG) is a rare autoimmune disease caused by autoantibodies against neuromuscular junction proteins; the nicotinic acetylcholine receptor (AChR), the muscle specific tyrosine kinase (MuSK) or the low-density lipoprotein receptor-related protein 4 (LRP4)." (PMID 25915571, 2015). "A clinical study investigating MuSK-CAAR T cells for myasthenia gravis is currently underway and actively recruiting patients (NCT05451212)." (PMID 40873568, 2025). "In the case of myasthenia gravis, anti-muscle-specific tyrosine kinase (MuSK) autoantibodies disrupt neuromuscular junction signaling, leading to muscle weakness." (PMID 40873568, 2025). "Double Seropositive Myasthenia Gravis (DSP-MG), a rare variant of Myasthenia Gravis (MG), is defined by the simultaneous presence of both anti-acetylcholine receptor (AChR) antibodies and anti-muscle-specific tyrosine kinase (MuSK) antibodies in the serum of affected individuals." (PMID 41159035, 2025). "In myasthenia gravis mediated by positive MuSK autoantibodies, IgG4 autoantibodies bind to the MuSK receptor and functionally block the transmission of neuromuscular signals." (PMID 41159035, 2025). "Muscle-specific kinase (MuSK) myasthenia gravis is a rare autoimmune disorder of the neuromuscular junction that predominantly affects the bulbar and respiratory muscles." (PMID 41476989, 2025). "There are some differences in the treatment of myasthenia gravis between MuSK antibody-positive and acetylcholine receptor (AchR) antibody-positive myasthenia gravis." (PMID 40103816, 2025). "We have also reported elevated blood MuSK immunoreactivity levels in patients and in a mouse model of myasthenia gravis, a disease characterised by impaired neurotransmission due to autoantibodies against NMJs." (PMID 40356623, 2025). "Cases of newly diagnosed MuSK-Ab-positive myasthenia gravis following SARS-CoV-2 infection have been reported in the literature." (PMID 41476989, 2025). "In the present case, the patient developed MuSK-Ab-positive myasthenia gravis approximately eight weeks after confirmed SARS-CoV-2 infection, with type II respiratory failure as the initial presentation." (PMID 41476989, 2025). "Background and aims: Rituximab, a monoclonal antibody targeting CD20 B cells, has a well‐established role in myasthenia gravis (MG) with muscle‐specific kinase receptor (MuSK) antibodies." (PMID 40542608, 2025). "Anti‐acetylcholine receptor (AChR) and anti‐muscle‐specific tyrosine kinase (MuSK) autoantibody detection is crucial in the diagnosis and choice of treatment of myasthenia gravis (MG)." (PMID 41287506, 2025). "Myasthenia gravis with positive MuSK antibody often involves the bulbar muscles and is usually refractory to acetylcholinesterase inhibitors." (PMID 38911858, 2024). "Muscle atrophy is an unusual but distinct feature of MuSK antibody-positive myasthenia gravis (MuSK-MG), primarily affecting facial muscles and the tongue." (PMID 38975540, 2024). "In myasthenia gravis, autoantibodies against muscle-specific kinase (MuSK), essential for neuromuscular transmission, play a pathogenic role." (PMID 39628482, 2024).